INS (insulin)
Diseases named in the same sentence as INS in open-access papers (continued):
Sharing a sentence is not in itself a finding about the gene and the disease.
Hypoglycemia (continued). "Among insulin-treated patients the frequency of hypoglycemia is greater in T1D than in T2D patients, and depends on intensive insulin treatment, regimens of insulin administration, and age." (PMID 34638984, 2021). "Insulin analogues, compared with human insulins, can better mimic endogenous insulin production and possibly contribute to reducing hypoglycemia and increasing patient satisfaction with treatment." (PMID 33320451, 2021). "Although the adverse brain effects of acute hypoglycemia while on insulin treatment in T1D has been well described, the effects of acute insulin deprivation on the brain and cognition remain to be determined." (PMID 33561011, 2021). "Normally, this is counteracted by a high rate of gluconeogenesis; however, in patients with HI, this is suppressed owing to inappropriate secretion of insulin, resulting in an imbalance of glucose homeostasis weighted toward hypoglycemia." (PMID 34435596, 2021). "Generally speaking, delayed insulin initiation despite of elevated HbA1c is common due to many reasons including side effects from weight gain or fear of hypoglycemia." (PMID 34457016, 2021). "They demanded information on management of hypoglycemia, interaction between insulin intake and physical exercise and precise nutritional information (regarding food labels, ration calculation, adjusting insulin intake, and the sensibility insulin factor)." (PMID 34898453, 2021). "It is challenging to maintain continuously the balance of carbohydrate intake, physical activity, and exogenous insulin, and hypoglycemia (low blood glucose) often occurs." (PMID 34444464, 2021). "The metformin group had lower prevalences of neonatal hypoglycemia, macrosomia, and NICU admission, while the glyburide group had a higher prevalence of neonatal hypoglycemia than insulin." (PMID 34641848, 2021). "Plasma glucagon levels were significantly elevated in hypoglycemia male [M-V/INS versus M-V/V] and female [F-V/INS versus F-V/V] rats." (PMID 33490375, 2021). "Carbohydrate loading before exercise can be problematic with glucose-responsive insulin delivery, often resulting in hypoglycaemia during exercise." (PMID 33550442, 2021). "In contrast, glucagon responses to insulin-induced hypoglycemia remain present, but diminished, in C-peptide–positive patients with T1D, with the magnitude of this response being proportional to the rise in C-peptide after a mixed-meal tolerance test." (PMID 34003799, 2021). "Iatrogenic hypoglycemia was defined as a BG measurement less than or equal to 70 mg/dL occurring within the pharmacologic duration of action of administered insulin, sulfonylurea, or meglitinide." (PMID 33416883, 2021). "Tumor cells produce insulin independently of glucose levels, consequently the clinical picture is characterized by symptoms of hypoglycemia, both autonomic and neuroglycopenic." (PMID 34199977, 2021). "The consistency that both somatostatin and insulin releases are stimulated linearly in a dose-dependent fashion by glucose is instrumental in preventing insulin-induced hypoglycemia." (PMID 33494193, 2021). "One hundred fourteen (47.1%) respondents reported a history of hypoglycemia after injecting insulin." (PMID 34690922, 2021). "One interesting area of future research would be to investigate the influence of basal insulin use on QoL, especially hypoglycemia outcomes and sleep quality, with more objective measures (e.g., actigraphy, polysomnography and continuous glucose monitoring)." (PMID 33550540, 2021). "GPR41 KO mice showed fasting hypoglycemia, consistent with increased basal and glucose-induced insulin secretion by islets in vitro." (PMID 34943862, 2021). "Given the prior history of type 2 diabetes, recent onset of symptomatic fasting hypoglycemia, and the inappropriately elevated serum insulin and C-peptide concentrations, a diagnosis of insulinoma was considered." (PMID 34583764, 2021).
Hypoglycemia (continued). "Despite the rapidly changing insulin requirements, close monitoring prevented any cases of symptomatic hypoglycemia." (PMID 34458301, 2021). "The levels of polypharmacy observed in this study are higher than those reported for the general Scottish population, even when excluding insulin and drugs for the management of hypoglycaemia." (PMID 33608768, 2021). "The phenotype study was particularly focused on glucose and insulin homeostasis: these mice displayed hypoglycemia in the fasted state secondary to impaired fasting-induced glucagon increased and impaired gluconeogenesis induction in the liver." (PMID 34201257, 2021). "Standard insulin therapy in T1DM is associated with increased complications, including hypoglycemia, weight gain, dyslipidemia, and insulin resistance." (PMID 34489478, 2021). "What is the incidence of sulfonylurea or insulin treatment deintensification among older adults after an episode of severe hypoglycemia?" (PMID 34726745, 2021). "Insulin plays, therefore, a pro-obesogenic role both from its anabolic effect on lipid accumulation and due to compensatory eating to prevent episodes of hypoglycemia." (PMID 33996288, 2021). "Maintaining normal blood glucose levels to avoid and/or reduce hypoglycemia episodes in response to exercise requires tight control of daily insulin injections as well as continuous monitoring of glucose levels." (PMID 34557162, 2021). "The difference in time to hypoglycemia and insulin dose between groups complicates the interpretation of between-group differences, although the rate of decline in plasma glucose was almost similar between the two groups." (PMID 34085953, 2021). "This suggests QTc-interval as a potential early marker of insulin-induced hypoglycaemia that need to be investigated further." (PMID 33727615, 2021). "Pairwise meta-analysis showed a significant lower prevalence of neonatal hypoglycemia in the metformin group than in the insulin group (RD − 0.07; 95% CI − 0.11, − 0.02)." (PMID 34641848, 2021). "All participants have a 4‐week run‐in period to optimize glycaemic control and to receive instruction in hypoglycaemia avoidance using insulin dose adjustment and real‐time continuous glucose monitoring (CGM)." (PMID 33532608, 2021). "We also demonstrate that AVP neuron activity is elevated during hypoglycemia induced by either 2DG or exogenous insulin." (PMID 34787082, 2021). "This is an important goal because insulin treatment is frequently responsible of discomfort in women with GDM for the multiple daily injections, for the risk of hypoglycemia and excessive maternal weight gain." (PMID 33893377, 2021). "The artificial pancreas system also demonstrated its ability to minimize moderate hypoglycemia excursions despite having to deal with an unannounced intravenous insulin injection." (PMID 32006145, 2021). "The mechanism of hypoglycaemia induced by many antimalarial drugs have been suggested to be related to increase in insulin secretion." (PMID 33778463, 2021). "Body weight reduction and basal insulin dose increase were identified as predictive factors for hypoglycaemia in a multivariable analysis." (PMID 33532606, 2021). "EIAS is a self-limiting disease and hypoglycemia can subside and disappear within a few months after discontinuing the related insulin." (PMID 33827670, 2021). "I occasionally felt hypoglycemia after conscious exercise and missed insulin injections in boarding school." (PMID 35002955, 2021). "An interesting finding of our study was that the rate of hypoglycemia remained unchanged over time in patients who already used insulin analogues." (PMID 33905628, 2021). "Respondents who had good knowledge of insulin self-administration were 46% less likely to develop hypoglycemia than those who had poor knowledge of insulin self-administration." (PMID 34690922, 2021). "Glucagon receptor antagonists can lower insulin needs while improving glucose time-in-range and decreasing hypoglycemia times." (PMID 34902055, 2021).
Hypoglycemia (continued). "As the insulin level rose, and hypoglycemia developed, blood beta‐hydroxybutyrate (βOHB) levels initially fell in parallel with the fall in FFA, and then rose slightly, once again paralleling FFA." (PMID 33769710, 2021). "In response to insulin-induced hypoglycemia in diabetic patients with autonomic neuropathy, the plasma levels of epinephrine and norepinephrine were significantly lower than in diabetics without autonomic neuropathy and healthy individuals." (PMID 34060586, 2021). "We show that the A1/C1 neurons of the medulla oblongata drive AVP neuron activation in response to insulin-induced hypoglycemia." (PMID 34787082, 2021). "Previous studies ascribed the reduced 18F-FDG uptake in tumors and inflammatory lesions with insulin-induced hypoglycemia to the effects of insulin, which shifts 18F-FDG from the original area to insulin-sensitive organs." (PMID 33795778, 2021). "The other participant, who would normally remove the pump while running, continued to use the pump with a reduction in the basal insulin rate as suggested by the app and experienced hypoglycemia." (PMID 34647896, 2021). "We next assessed the risk of hypoglycemia associated with treatment by MVL(F+E+I) and insulin solution." (PMID 35056918, 2021). "We found that the hormonal and metabolic responses are still intact following CHADN, allowing a normal response to insulin‐induced hypoglycemia." (PMID 33769710, 2021). "There is considerable evidence that experimental and spontaneous insulin-induced hypoglycemia affects cardiac repolarization." (PMID 33898141, 2021). "After 8 weeks of insulin treatment, he began to present episodes of hypoglycemia and required a reduction of the initial insulin dose." (PMID 33905625, 2021). "The main indication for glucagon is hypoglycemia in insulin-treated diabetic patients; however, congenital hyperinsulinism and alimentary hypoglycemia in infants are also amenable to glucagon." (PMID 34638984, 2021). "Self-reports of the frequency of hypoglycemia episodes were explored further by insulin regimen group and by blood glucose monitoring methods." (PMID 34557162, 2021). "The percentage of patients with hypoglycemia (including severe and nocturnal) was comparable across groups divided according to duration of use of insulin analogues." (PMID 33905628, 2021). "Some also feel that taking insulin prevents them from performing religious fasting practices out of the fear of hypoglycemia." (PMID 33444368, 2021). "The greatest reductions in hypoglycemia with closed-loop were observed in participants with the highest levels of hypoglycemia during the standard insulin therapy period." (PMID 34349267, 2021). "Along with the emerging of the new generation of insulin analogues (degludec and glargine U300) came the comparisons between these two insulins, mostly in terms of incidence of hypoglycaemia, and pharmacokinetic/pharmacodynamic (PK/PD) characteristics." (PMID 33926446, 2021). "There are two favorable outcomes of such combinations of insulin with other medicines: reducing the incidence of hypoglycemia during insulin therapy and achieving euglycemia with lower insulin doses." (PMID 34068151, 2021). "Glucagon secretion is observed to be reduced in patients with T1DM, with an increasing risk of insulin-induced hypoglycemia, but it is enhanced in T2DM, exacerbating the effects of reduced insulin release and action on glucose of blood levels." (PMID 34295899, 2021). "Insulin-induced hypoglycemia significantly increased Fos immunoreactivity in both Chow-fed rats (23.6 ± 4.8%, p = 0.0001) and KD-fed rats (20.9 ± 1.8%, p = 0.0007)." (PMID 34444787, 2021). "Tight glucose control is key to avoiding long-term complications, but fear of hypoglycemia due to overdosing on insulin remains a limiting factor." (PMID 35082757, 2021).
Hypoglycemia (continued). "It was observed that recurrent hypoglycemia evokes significant alterations in the brain cortical metabolism, mitochondria content and dynamics, and significantly impacts insulin-mediated downstream signaling pathways." (PMID 34948265, 2021). "The enrichment analysis of GO biological processes showed that regulation of insulin secretion, glucose homeostasis, apoptosis, nitric oxide biosynthesis and cell signaling are significantly enriched for hypoglycemia." (PMID 34830301, 2021). "Although it is tempting to start patients on higher doses, especially if their body mass index is >35 kg/m2, starting with lower doses and ascertaining the patient’s responsiveness to insulin is prudent to avoid hypoglycemia." (PMID 34165382, 2021). "The difference in the dose of insulin required to induce hypoglycemia reflects a relatively high daily insulin dose in these high insulin-resistant patients." (PMID 34085953, 2021). "Despite the small sample sizes, less unscheduled consultations in insulin-treated patients indicates that this special subgroup, which usually needs closer monitoring, was probably less afraid of hypoglycemia and probably felt more secure with the treatment." (PMID 34448717, 2021). "In this case study a 38-year-old nulliparous woman with insulin requiring gestational diabetes developed hypoglycaemia after consuming raspberry leaf tea (2 cups per day for three days) at 32 weeks gestation." (PMID 33563275, 2021). "Congenital hyperinsulinism (CHI) is a genetically heterogeneous disease in which intractable, persistent hypoglycemia is induced by excessive insulin secretion and an increase in serum insulin concentrations." (PMID 33502730, 2021). "Hypoglycemia occurs when the homeostatic balance between insulin intake and body’s physiological need is disrupted." (PMID 34067715, 2021). "The three most common reasons for discontinuing insulin therapy among patients were deterioration of T2DM and causing complications, hypoglycemia, and needle injections." (PMID 34712538, 2021). "Most importantly, local perfusion of glucose into the VMH prevented CRR following insulin-induced hypoglycemia." (PMID 34265067, 2021). "In clinical practice, it is wise to use insulin for glycemic control at the lowest optimal dose so as to avoid hypoglycemia and excess insulin in the blood." (PMID 34356646, 2021). "A temporary discontinuation of diazoxide at the age of three years showed high insulin levels up to 164.5 pmol/L in hypoglycemia." (PMID 34576089, 2021). "The participants changed the way they adjusted their insulin doses in connection with exercise and claimed that it had reduced incidences of hypoglycemia after the camp." (PMID 36994325, 2021). "In the last few years, brain hypoglycemia and alterations of the brain insulin signaling pathway, including brain insulin resistance, are emerging as common mechanisms of neurodegeneration in DS and AD." (PMID 33670211, 2021). "Glucose is administered as glucose–insulin (GI) therapy for hyperkalemia to stimulate endogenous insulin secretion and prevent hypoglycemia." (PMID 34063969, 2021). "SSR149415 treatment abolished insulin-induced glucagon secretion, showing that intact AVP/V1bR signaling is required for efficient glucagon release following insulin-induced hypoglycemia." (PMID 34752420, 2021). "When considered in the context of the current results, it is possible that the glucagon responses to insulin-induced hypoglycemia would be proportional to the quantity of residual C-peptide." (PMID 34003799, 2021). "Most, but not all, studies have demonstrated that C-peptide positivity confers a protective effect against insulin-induced hypoglycemia." (PMID 34003799, 2021). "Glucose tolerance tests and hyperinsulinemic-euglycemic and hypoglycemic clamps were used in Sprague-Dawley rats to assess insulin sensitivity and hypoglycemia counterregulation, respectively." (PMID 34975743, 2021).
Hypoglycemia (continued). "Preclinical and clinical studies have shown that insulin-induced hypoglycemia leads to increased plasma AVP levels." (PMID 34752420, 2021). "Hypoglycemia in the 12 months before admission was higher in insulin-based therapy patients (66.1%; p = 0.001)." (PMID 33402217, 2021). "Acetylsalicylic acid and flufenamic acid also produce hypoglycemia due to increased insulin secretion and decreased gluconeogenesis by liver and reduced insulin clearance." (PMID 34070633, 2021). "The device provides trend arrows that add context to each glucose reading; this has a critical impact on insulin dosing decision and hypoglycemia prevention." (PMID 33743082, 2021). "Several studies have explored the antidiabetic potential of PACAP due to the modulation of glucose-induced insulin secretion, the proliferation of islet cell mass, and increased glucagon response to insulin-induced hypoglycemia." (PMID 33809145, 2021). "In isolated rat brain microvessels, insulin-induced hypoglycemia also activates upregulation of GLUT1 protein levels and in addition an accumulation of GLUT1 at the luminal membrane." (PMID 34032568, 2021). "Of the patients who take insulin, type 1 diabetics are three times more likely to experience hypoglycemia as compared to type 2 diabetics." (PMID 33466659, 2021). "Hypoglycemia episodes, fear of hypoglycemia scores, insulin therapy (pump vs. injection) and blood glucose monitoring (continuous blood glucose monitors [CGMs] vs. blood glucose meters) methods are reported in the present work." (PMID 34557162, 2021). "Increased endogenous insulin production results in reduced daily insulin doses, better metabolic control, and adverse effects of insulin therapy, primarily hypoglycemia." (PMID 34959363, 2021). "The objective of this analysis was to evaluate insulin suspension events and related hypoglycemia treatment and glycemic responses during the use of an investigational PLGS insulin management system." (PMID 33535013, 2021). "The highest proportion of patients (n = 1854 (78.5%)) with nocturnal hypoglycaemia were on insulin treatment." (PMID 33672913, 2021). "This study aimed to evaluate the effectiveness of health education on knowledge about hypoglycemia and insulin pen use among outpatients with T2DM at a primary care hospital in Vietnam." (PMID 34497858, 2021). "On the other hand, hypoglycemia stimulates GH release, and insulin-induced hypoglycemia can be used to assess the integrity of GH secretion." (PMID 34199514, 2021). "Data were collected at baseline and the end of every year including glycated hemoglobin (HbA1c), insulin dose, lipid profile, blood pressure, and adverse events (severe hypoglycemia and DKA)." (PMID 33859614, 2021). "Plasma glucose, glucagon, C-peptide, insulin, epinephrine and platelet aggregation responses were measured before, during and after hypoglycaemia." (PMID 33727615, 2021). "Several experts advise to lower the dose of sulfonylurea and short-acting and low-acting insulin analogues prior to or during titration of GLP-1RA therapy, to reduce the risk of (severe) hypoglycemia." (PMID 34305810, 2021). "The main finding from the hypoglycaemic clamps was an augmented responsiveness of the cortisol axis to hypoglycaemia among overweight and insulin-resistant participants compared with lean and more insulin-sensitive participants." (PMID 33241460, 2021). "One month and two months after this intervention, knowledge about hypoglycemia and insulin pen use were recorded again." (PMID 34497858, 2021). "There were still recurrent episodes of hypoglycemia after stopping exogenous insulin for longer than 5 half-lives." (PMID 33827670, 2021). "These include changes in peripheral insulin sensitivity, hypoglycaemia-glucagon feedback loops, gastric emptying, glucose intestinal absorption and the incretin effect." (PMID 34203471, 2021). "Hypoglycemia is one of the most frequent acute complications of insulin therapy which arouses anxiety." (PMID 34070638, 2021).